VDR (vitamin D receptor)
Diseases named in the same sentence as VDR in open-access papers (continued):
Sharing a sentence is not in itself a finding about the gene and the disease.
injury (3 papers, 2021 to 2023). Damage inflicted on the body as the direct or indirect result of an external force, with or without disruption of structural continuity. "In the literature, vitamin D supplementation was shown to increase VDR and ACE2 mRNA expression in a murine model of lipopolysaccharide-induced acute lung injury, suggesting a protective role of vitamin D against acute lung injury." (PMID 36014781, 2022).
leukoplakia (3 papers, 2015 to 2025). A white patch or plaque on a mucous membrane that cannot be characterized clinically or pathologically as any other disease. "VDR polymorphism markedly diminishes the risk of oral disorders, especially the risk of leukoplakia, a form of precancerous oral lesion." (PMID 40356850, 2025).
lower respiratory tract infections (3 papers, 2012 to 2022). "Polymorphism of the vitamin D receptor gene is associated with serum 25(OH)D levels and the receptor genotype influences the risk of upper and lower respiratory tract infections." (PMID 30866564, 2019). "However, the FokI, and TaqI Vitamin D receptor polymorphisms have been shown to be associated with lower respiratory tract infections in children." (PMID 22726649, 2012).
lumbar disc herniation (3 papers, 2018 to 2023). "Specifically, we examined the FokI VDR polymorphism and its potential association with lumbar disc herniation (LDH) in patients from Bulgaria." (PMID 37868452, 2023). "The patients with LDD were divided into three subgroups (subgroup 1: lumbar disc herniation; subgroup 2: lumbar spinal stenosis; subgroup 3: lumbar spondylolisthesis) to further probe the association of plasma VDR levels and VDR gene polymorphisms and LDD." (PMID 31127184, 2019). "Association of Vitamin D receptor (VDR) polymorphisms with lumbar disc herniation (LDH) have been identified in several ethnic groups globally." (PMID 30356314, 2018).
male infertility (3 papers, 2022 to 2024). The inability of the male to effect fertilization of an ovum after a specified period of unprotected intercourse. "Among these studies, 18 investigated the association of VDR genetic polymorphisms with female infertility, 2 with male infertility, and 4 with miscarriage." (PMID 38816754, 2024). "The expression of the VDR in the male reproductive system and spermatozoa led researchers to investigate the VDR methylation signatures in association with reproductive disorders, including male infertility." (PMID 38203278, 2023). "Published data reported a negative correlation between the seminal methylation status of CGI2, located in the VDR promoter region, and both sperm concentration and progressive motility, strengthening the potential role of this epigenetic mechanism in male infertility." (PMID 38203278, 2023). "In particular, the presence of VD metabolizing enzymes in all reproductive tracts suggested the importance of locally regulated VD metabolism and also the evidence of VDR expression in the testis supported a VD role in influencing male infertility by autocrine and paracrine action." (PMID 36014783, 2022).
measles (3 papers, 2018 to 2021). A highly contagious viral infection caused by the measles virus. "But in another cohort, they proposed that particular allelic differences and haplotypes of the vitamin D receptor genes could affect adaptive immune responses to measles vaccines among children in the United States." (PMID 33121844, 2021). "Furthermore, significant associations were shown between multiple vitamin D receptors (VDR) and retinoid X receptor α (RXRA) SNPs/haplotypes and measles-specific IL-2, IL-6, IL-10, IFN-α, IFN-γ, IFNλ-1, and TNF-α cytokine secretion." (PMID 33167413, 2020).
metastatic cancers (3 papers, 2020 to 2024). A carcinoma which has spread from the original site of growth to another anatomic site. "In both primary and metastatic cancers VDR nuclear and cytoplasmic immunostaining decreased in comparison to normal epithelia." (PMID 33227893, 2020). "Additionally, patients with multiple metastatic cancers had a significantly lower bone metastatic nuclear VDR expression in this study." (PMID 36362766, 2022). "Similar to the VDR expression, CYP24A1 expression was significantly decreased in patients with multiple metastatic cancers." (PMID 36362766, 2022).
mood disorder (3 papers, 2015 to 2025). A cognitive disorder a disturbance in which the person's mood is hypothesized to be the main underlying feature. "VD as changes in VDR impact on various brain neurotransmitters, and thus suggest a potential role of vitamin D in causing and redressing mood disorders." (PMID 30967121, 2019). "Research directed towards investigating the role of VDR in regulating the periphery and CNS immune response in relation to mood disorders is suggested." (PMID 26217190, 2015). "Despite the substantial amount of evidence linking VDR and the immune response, its role in the regulation of the inflammatory response in mood disorders remains to be elucidated." (PMID 26217190, 2015). "Further research investigating the role of VDR in mood disorders is warranted." (PMID 26217190, 2015).
myoma (3 papers, 2021 to 2025). "In fact, the levels of VDR in the uterine myoma samples were significantly lower than the levels in the adjacent myometrial samples." (PMID 40868086, 2025). "A previous VDR study showed that only 25 women (60%) had a reduction in VDR expression in myoma cells compared to the adjacent healthy tissue." (PMID 36014877, 2022). "In their study, the levels of VDR in the uterine myoma samples were significantly lower than the levels in the adjacent myometrial samples, similar to the results of the present study." (PMID 33952298, 2021). "Furthermore, the vitamin D/VDR complex regulates the expression of genes also involved in myoma pathogenesis." (PMID 36014877, 2022). "However, the expression of VDR in non-myoma uterine muscle has not previously been investigated." (PMID 36014877, 2022).
nasal polyps (3 papers, 2023 to 2025). "Expression of the VDR gene expression may be implicated with the pathophysiological mechanisms of nasal polyposis." (PMID 37908960, 2023). "Human sinonasal fibroblasts are VDR-expressing cells thought to be involved in the etiology of CRS with nasal polyps." (PMID 38601384, 2024). "It was concluded that VDR gene expression might be related to the pathogenesis or progression of nasal polyps." (PMID 37908960, 2023). "A statistically significant reduction in vitamin D receptor (VDR) nuclear staining in patients with CRS without nasal polyps and CRS with nasal polyps compared to controls, as well as the existence of VDR protein expression in the sinonasal mucosa." (PMID 38601384, 2024).
oesophageal cancer (3 papers, 2017 to 2023). "The association between VDR expression and prognosis was not impacted by tumour location, race, pathological type, or cut-off value, though the predictive effect of VDR seems more significant in oesophageal cancer." (PMID 37561808, 2023). "Although some of the studies included in this meta-analysis indicated that VDR expression is not related to prognosis of oesophageal cancer, the pooled result indicated high VDR expression to be associated with better OS." (PMID 37561808, 2023).
Osteochondrosis (3 papers, 2017 to 2025). Abnormal growth ossification centers in children. "In a previously published paper, we observed an association between the VDR polymorphism rs2228570, previously named FokI, and discopathies in general and/or osteochondrosis concomitant with disc herniation." (PMID 40725395, 2025). "The interesting finding regarding the functional FokI VDR polymorphism was the observation of higher CTx-II levels in F allele carriers osteochondrosis patients compared with healthy controls." (PMID 28961166, 2017). "Moreover, our results indicate that the focus should be directed to specific subgroups of LBP patients, particularly on those with osteochondrosis, as this condition appears more influenced by the different specific VDR polymorphisms." (PMID 28961166, 2017). "Of note, polymorphisms in the vitamin D receptor gene (VDR) have been showed to be associated with LBP and particularly with spine pathologies involving the IVD, such as herniation and discopathies, or affecting both IVD and endplate, such as osteochondrosis." (PMID 28961166, 2017). "Consistently with frequencies of VDR polymorphisms observed in a previously published larger study of Italian LBP patients, the TT and Aa genotypes, and the T and b alleles were more frequently found in patients with osteochondrosis than in healthy controls." (PMID 28961166, 2017).
osteonecrosis (3 papers, 2018 to 2024). A none disease characterized by death of bone tissue due to a lack of blood supply. "Confirming the finding in this study, the VDR T mutant allele showed association with the incidence of glucocorticoid-induced osteonecrosis with a P-value of 0.0025." (PMID 30533396, 2018). "Among various SNPs, only polymorphisms in the VDR and TYMS were independent predictors for osteonecrosis." (PMID 30533396, 2018). "Genetic polymorphisms in several genes including SERPINE1, VDR, CYP3A4, TYMS, PAI 1, and ACP 1 were documented to be associated with osteonecrosis." (PMID 30533396, 2018). "This study aimed to investigate the relationship between vitamin D receptor fok1 (VDR fok1) and thymidylate synthase (TYMS) gene polymorphisms with the glucocorticoid (GC) induced osteonecrosis (ON) in Egyptian pediatric ALL patients." (PMID 30533396, 2018). "Multiple candidate gene studies have indicated several polymorphisms in genes putatively related to the development of osteonecrosis, such as SERPINE 1, vitamin D receptor (VDR), and CYP3A4." (PMID 30251958, 2019). "VDR fok1 genotype was not previously studied in relation to glucocorticoid-induced osteonecrosis among the Egyptian population; neither in children nor in adults." (PMID 30533396, 2018). "VDR fok1 and TYMS tandem repeats in cases with osteonecrosis vs. controls (N = 102)." (PMID 30533396, 2018).
pancreatic adenocarcinoma (3 papers, 2015 to 2024). "We analyzed the TCGA database to examine the association between VDR expression and immune cell infiltration in pancreatic adenocarcinoma (PAAD)." (PMID 38600588, 2024). "A single study looking at the impact of VDR expression on survival in pancreatic adenocarcinoma performed in a Chinese population of 61 patients found that patients with high VDR expression survived longer than those with low or no VDR expression." (PMID 30344947, 2018).
peritonitis (3 papers, 2014 to 2019). Inflammation of the peritoneum (tissue that lines the abdominal wall and covers most of the organs in the abdomen). "VDR, an endogenous regulator of NLRP3, mitigates inflammasome-related inflammation in vivo, such as LPS-induced systemic inflammation and alum-induced peritoneal inflammation." (PMID 31866999, 2019). "We next addressed the negative role of VDR in NLRP3 inflammasome activation using an alum-induced peritonitis model." (PMID 31866999, 2019).
primary sclerosing cholangitis (3 papers, 2017 to 2024). "We investigated the incidence of VDR polymorphisms (rs1544410-BsmI; rs7975232-ApaI; rs731236-TaqI) in a group of patients with primary sclerosing cholangitis (PSC, n = 275) and in healthy controls (n = 376)." (PMID 28426778, 2017). "The colon of patients with primary sclerosing cholangitis exhibited an upregulation of miR‐346, potentially leading to the disturbance of the vitamin D receptor and Tumor necrosis factor‐α signaling pathway." (PMID 38934856, 2024).
promyelocytic leukemia (3 papers, 2010 to 2020). "The observation, consistent with our previous studies in the HL-60 promyelocytic leukemia cells, demonstrates that VDR resides predominantly in the cytoplasm of the pig parathyroid cells in the absence of VDRAs, and VDRA treatment induces VDR to translocate into the nucleus." (PMID 20204178, 2010).
pterygium (3 papers, 2021 to 2025). A wedge-shaped fibrovascular lesion arising from the bulbar conjunctiva and extending to the cornea. "Studies with a larger sample of different stages of pterygium tissue are needed to further elucidate the exact effect of VDR transcriptional activity on immunomodulation linked to the anti-inflammatory effect of vitamin D in pterygium." (PMID 40507396, 2025). "The vitamin D receptor eexpression levels inpterygium tissue, blood vitamin D levels, and frequency of selected vitaminD receptor gene polymorphisms (BsmI, FokI, andTaqI) were compared between patients with pterygium andhealthy participants." (PMID 33567021, 2021). "Data regarding VDR polymorphisms in patients with pterygium are limited in theexisting literature." (PMID 33567021, 2021). "In the epithelial cells of pterygium patients, VDR was localized both in the nucleus and cytoplasm, which was indicative of increased transcriptional activity." (PMID 40507396, 2025). "Two separate studies have demonstrated differential expression and localization of VDR in epithelial and endothelial cells of patients with pterygium despite unaltered serum 25-OHD levels." (PMID 40507396, 2025). "Based on their results, the authors concluded that there is a possibility that in pterygium, nuclear VDR represents an alternative pathway through which vitamin D regulates gene expression through its anti-proliferative and anti-inflammatory effects." (PMID 40507396, 2025). "Immunohistochemical assays found VDR localization to differ significantly in the pterygium cells compared to normal conjunctival cells." (PMID 35684153, 2022). "In healthy conjunctiva, VDR was localized mainly in the cytoplasm, while in pterygium cells, VDR was co-localized in the nucleus and cytoplasm." (PMID 35684153, 2022). "Further analyses and clinical trials are needed to standardize the role of VDR in pathogenesis and the development of pterygium." (PMID 35684153, 2022). "The serum vitamin D levels were measured for both groups.Immunohistochemical staining for vitamin D receptor ewas performed onsections obtained from the pterygium and adjacent healthy conjunctivaltissues of the same individuals." (PMID 33567021, 2021). "VDR haplotypes andup-regulation in pterygium tissue can play a role in the pathogenesis of thisdisease." (PMID 33567021, 2021). "Additionally, tissue expression of VDR was upregulated in pterygium intravascular inflammatory cells, endothelial cells of micro-vessels, and subepithelial stroma in comparison to normal conjunctiva." (PMID 40507396, 2025). "This study aimed to determine the role of vitamin D receptor in thepathogenesis of pterygium." (PMID 33567021, 2021). "Hence, the nuclear signaling pathways related to VDR may be engaged in the pathogenesis of pterygium." (PMID 35684153, 2022). "They hypothesized that pterygium resembles benignneoplastic disorders, so that the nuclear immunolocalization of VDR may represent analternative nuclear pathway that is related to anti-proliferative andanti-inflammatory effects via the regulation of gene expression." (PMID 33567021, 2021). "However, vitamin D receptor polymorphismanalysis in patients with pterygium did not reveal any significantdifference in BsmI, FokI, or TaqIpolymorphisms in comparison with the healthy volunteers." (PMID 33567021, 2021). "Furthermore, when compared with the control group, significantly higher expression of immunohistochemical staining for VDR was shown in the cytoplasm of the pterygium group, while in the control group, most samples were not positive for nuclear immunoreactivity." (PMID 40507396, 2025).
retinoblastoma (3 papers, 2016 to 2021). A malignant tumor that originates in the nuclear layer of the retina. "In an in vitro study of retinoblastoma tissue expressing VDR, supplementation with vitamin D resulted in a reduction of growth and apoptosis of the retinoblastoma cells." (PMID 26885530, 2016). "Ligands that can activate the VDR/RXR such as 9-cis RA and vitamin D analogues have been shown to inhibit cell proliferation in a retinoblastoma cell line and attenuate tumor growth in a xenograft model of human Rb respectively." (PMID 34003213, 2021). "The VDR gene is expressed in a number of ocular structures such as the retina, the cornea and the RPE-choroid and in ocular cell lines such as ARPE-19 and human retinoblastoma (Y79), thus demonstrating its regulatory function in the ocular system." (PMID 31450606, 2019).
sarcoidosis (3 papers, 2014 to 2020). Sarcoidosis is a multisystemic disorder of unknown cause characterized by the formation of immune granulomas in involved organs. "In this study, alveolar macrophage–cathelicidin mRNA expression, VDR, and the VDR coactivator steroid receptor coactivator-3 (SRC3) were measured by quantitative PCR in alveolar macrophages from bronchoalveolar lavage in patients with biopsy-proven sarcoidosis and healthy controls." (PMID 33659946, 2020).
schistosomiasis (3 papers, 2019 to 2022). An infectious disease caused by parasitic trematodes of the genus Schistosoma that colonize human blood vessels and release eggs that can cause granulomatous reactions leading to acute (swimmer's itch or acute schistosomiasis syndrome) or chronic disease. "During the initial phase of Schistosomiasis, IFN-γ negatively regulates mmu-miR-351-3p in hepatic stellate cells (HSCs), facilitating the expressions of vitamin D receptor (VDR) and SMAD7 TGF-β/SMAD signaling antagonists and blocking the activation of HSCs." (PMID 36677353, 2022).
seminoma (3 papers, 2018 to 2023). A radiosensitive malignant germ cell tumor found in the testis (especially undescended), and extragonadal sites (anterior mediastinum and pineal gland). "RNAseq analysis of VDR genes and TCGA mRNA expression of Vitamin D regulatory genes were clearly able to discriminate pure seminomas from NSGCT." (PMID 37242266, 2023). "The frequency of genomic alterations in genes in the VDR gene signature between seminomas and NSGCTs was comparable: in total, 70% and 63.1% of seminomas and NSGCTs, respectively, had a least one alteration in this gene set." (PMID 37242266, 2023). "Clustering analyses of these VDR expression signatures were clearly able to discriminate pure seminomas from NSGCT." (PMID 37242266, 2023). "Thus, a prospective study is planned to correlate iChr12p formation with altered VDR gene signature in seminoma and NSGT via RNAseq." (PMID 37242266, 2023). "This shows that the differential activation of VDR signatures genes in seminomas and NSGCTs might be the result of GCT subtype-specific concentrations of 1,25(OH2)D3." (PMID 37242266, 2023). "Interestingly, the expression of VDR was significantly higher in NS than in seminoma (p < 0.0001)." (PMID 29765521, 2018). "Interestingly, the expression of VDR was much higher in non seminoma than in seminoma tissue." (PMID 29765521, 2018). "Underlining the possible association between vitamin D metabolism and iChr12p formation, previous immuno-histochemistry (IHC) analysis showed that VDR expression was significantly lower in pure seminoma, and not present in GCNIS, compared to NSGCT." (PMID 37242266, 2023). "Interestingly, VDR gene expression alone was not able to discriminate between pure seminoma and NSGCT types, leading to the conclusion that its expression and, especially, its activity are likely regulated at the post-transcriptional and/or endocrine level." (PMID 37242266, 2023). "RNAseq analysis of Vitamin D receptor (VDR) genes from the TCGA cohort revealed that clustering of VDR expression signatures could differentiate between pure seminomas and non-seminomatous germ cell tumors (NSGCT)." (PMID 37242266, 2023). "Based on the result that differential transcriptional programs of the VDR and non-genomic actions of Vitamin D3 correlate with the histology subtype, we tested whether Vitamin D3 treatment may affect the proliferative capacity of seminoma and NSGCT cell lines." (PMID 37242266, 2023).